AKT1 (AKT serine/threonine kinase 1)
Diseases named in the same sentence as AKT1 in open-access papers (continued):
Sharing a sentence is not in itself a finding about the gene and the disease.
cancer (continued). "Treatment with YN1 decreased the expression of several genes, including Pi3kca, Akt1 glycolytic enzymes such as the pyruvate kinase isoform M2 (PKM2) which is encoded by the Pkm gene, and is expressed exclusively in embryonic stages, proliferating cells, and cancer cells." (PMID 38007516, 2023). "Therefore, a comprehensive understanding of the role of post-translational modification in the regulation of Akt1 could help the design of new strategies for cancer therapy." (PMID 37633993, 2023). "Amongst the four phytocompounds, tehranolide has better potential to suppress the expression of AKT1 and could be used for anti-cancer drug development, as inhibition of AKT1 is directly associated with the inhibition of growth, progression, and metastasis of the tumor." (PMID 36985568, 2023). "The seven prevalent ‘candidate genes’ (ADAM10, ADAM17, AKT1, CTNNB1, ESR1, FGFR1, PIK3CA) showed direct associations with enriched terms under the categories of ‘Neurodegenerative disorders’, ‘Neurodevelopmental diseases’, ‘CNS tumour/cancer’ and ‘Cellular Signaling pathways’." (PMID 36229517, 2022). "Besides, a study has reported that AKT1 E17K is a therapeutic target in many cancers." (PMID 35387130, 2022). "In addition, genetically depleting or pharmacologically inhibiting AKT1 could robustly attenuate PDK1-S549A-induced cancer cell colony formation." (PMID 35318320, 2022). "In addition, one study identified GLI3 as an effector of KRAS/PI3K/AKT1 signaling in cancer cells." (PMID 36139698, 2022). "This phenomenon may indicate that the carrier of AKT1 rs1130233 dominance model has a low risk of cancer and is not prone to distant metastasis, which may indicate they have a long survival time." (PMID 34150619, 2021). "Furthermore, NMD inhibition has been proposed as a therapeutic approach for cancers, and this inhibition might be achieved with AKT1 inhibitors." (PMID 34634811, 2021). "In addition, SMYD3 can methylate lysine 14 on the AKT1 kinase, which promotes its phosphoactivation and plasma membrane accumulation, suggesting that SMYD3 methyltransferase activity may trigger the constitutive activation of AKT1 in cancer cells." (PMID 34503239, 2021). "Interestingly, some reports also have suggested that Akt1 might target some proteins, such as β-catenin and cyclin D1, to alter the progression of cancer through regulating cell proliferation and migration." (PMID 33911067, 2021). "Additionally, previous reports have illustrated that AKT1 could modulate EMT progress in human cancers." (PMID 32193155, 2020). "Overall, these data imply that SMYD3-mediated methylation of AKT1 at lysine 14 is essential for AKT1 activation and suggest that the inhibition of this methylation pathway may be a promising strategy to develop anti-cancer drugs." (PMID 31935919, 2020). "Furthermore, AKT1 and 2 seem to bear distinct or diversified effects in cancer progression." (PMID 33266015, 2020). "Considering the fact that Akt1 depletion resulted in increased apoptosis, reduced primary tumor size, and a lower frequency of vascular invasion and lung metastasis, it is possible that these DCs might be normally suppressed by Akt1 in cancer and/or immune cells." (PMID 33110146, 2020). "Further, when stratified by exogenous E use, carriers of the AKT1 rs2494738 T and rs2498789 C alleles had an increased risk of CRC among nonusers; however, in E+P users, carriers of the rs2494738 T allele had a reduced risk of CRC (with 30% of the SNP–cancer association explained by insulin level)." (PMID 29023587, 2017).
cancer (continued). "Similarly, mutations of Akt1, but not of Akt2 or Akt3 genes are significantly increased in a number of human cancers, although the clinical significance of those mutations is still to be established." (PMID 28903409, 2017). "In addition, Akt1 and Akt2 kinases have received much attention in the study of cancer because they are key mediators of the PI3K-signaling pathway, which is involved in the regulation of cell cycle, proliferation, apoptosis, protein synthesis and glucose metabolism." (PMID 28858257, 2017). "Therefore, the present meta-analysis analyzed the associations of SNPs in the 5′upstream regulatory or promoter region (mTOR rs2295080, AKT1 rs2494752), and 3′UTR region (mTOR rs2536, pTEN rs701848 and AKT1 rs2494750) in the mTOR signaling pathway (AKT, and PTEN) with cancer risk." (PMID 29259266, 2017). "Thus, TCRP1 may be a candidate as human oncoprotein that promotes cancer development by activation of PDK1/AKT1 signaling." (PMID 28436990, 2017). "Besides, we confirmed that the SMYD3 inhibitor BCI-121 significantly diminished Thr 308 phosphorylation levels of AKT1; this inhibitor effectively repressed the growth of cancer cells overexpressing SMYD3, further supporting the potential of SMYD3 as a target of anti-cancer drug development." (PMID 27626683, 2016). "While six of these patients had further alterations which likely contribute to cancer development (e.g. truncating mutation in tumor suppressor and/or copy number alterations), no cause other than AKT1 could be identified for the remaining six cases." (PMID 27515171, 2016). "However, the degree of functional redundancy between Akt1, Akt2, and Akt3 in cancer cell survival, proliferation and invasion remains unclear." (PMID 26234648, 2015). "The existence of an alternative promoter that drives the expression of the unique AKT1m transcript may provide a mechanism by which the levels of AKT1 can be temporally and spatially regulated at particular physiological states, such as cancer, where a heightened activity of this kinase is required." (PMID 24628780, 2014). "This phenomenon was somewhat supported by a recent study which found that BRAF mutations represented early events in thyroid carcinogenesis, whereas mutations of PIK3CA and AKT1 were latter events not found in the primary cancers, but in metastases or recurrent cancers." (PMID 22007340, 2012). "Potential roles of targets including Akt1, PPARG, and EGFR, as well as pathways related to cancer and lipid metabolism, were further indicated by network pharmacology and molecular docking." (PMID 42198446, 2026). "Western blot (WB), Polymerase Chain Reaction (PCR), and immunofluorescence (IF) were employed to evaluate the effects of lactate on the expression of ESM1, Akt1, and Cyclic GMP-AMP Synthase (cGAS) pathway-related proteins in cancer cells." (PMID 41930148, 2026). "Akt1 plays a crucial role in the PI3K/Akt/mTOR signaling pathway, which is often dysregulated in numerous human cancers." (PMID 40798865, 2025). "These hybrids exhibit a competitive profile on the STAT3 receptor, making them promising candidates for strategies aimed at the simultaneous suppression of the AKT1 and MAPK pathways, particularly in cancer treatment." (PMID 41155587, 2025). "Network pharmacology analysis identified AKT1 (serine/threonine protein kinase 1) and GAPDH as key hub genes involved in OC, with AKT1 playing a crucial role in the PI3K/Akt signaling pathway, which is often dysregulated in cancers." (PMID 40933552, 2025). "The AKT1 and Bcl-2 proteins are overexpressed in OSCC tissues and can promote cancer cell survival and proliferation." (PMID 41020907, 2025).
cancer (continued). "These interactions suggest potential inhibitory effects on AKT1 and GAPDH activity, which are involved in cancer cell survival and metabolic pathways, respectively." (PMID 40933552, 2025). "Among these, the top 60 proteins exhibiting significant p-values revealed high expression levels of phosphorylated AKT1, along with members of the STK family and LATS2 under the altered respiratory metabolism of cancer cells." (PMID 39922804, 2025). "Aberrant Akt1 activity resulting from the negative regulator of Akt, inactive phosphatase and tensin homolog (PTEN), leads to cancer development." (PMID 40148800, 2025). "Distinct AKT isoforms exhibit variable effects on tumorigenesis and cell migration, with AKT1 suppressing cancer cell migration and AKT2 promoting it." (PMID 38287309, 2024). "The core signaling pathways included pathways in cancer, the PI3K-Akt signaling pathway, and the AGE-RAGE signaling pathway in diabetic complications, involving genes such as AKT1, IL6, JAK2, and MAPK1." (PMID 39338337, 2024). "The role of the circadian clock in regulating cancer driver pathways, such as MYC and AKT1, in PDA, has been suggested by experimental models of PDA carcinogenesis." (PMID 38716727, 2024). "pDNA encoding shRNA that silences genes involved in cancer survival and growth, such as AKT Serine/Threonine Kinase 1 (Akt1), Vascular Endothelial Growth Factor (VEGF), and EGFR, exhibits anti-cancer effects." (PMID 39407665, 2024). "The restoration of AKT1 autoinhibition using small molecule inhibitors, such as Ipatasertib (GDC-0068), MK-2206, and triciribine has proven highly successful in cancer treatment." (PMID 39192607, 2024). "Our findings indicate that silibinin effectively suppresses the expression of EGFR mRNA, a crucial compound in the PAM signaling pathway, along with several downstream genes, including PI3K, AKT-1, PTEN, and mTOR mRNAs, in cancer cells." (PMID 38504785, 2024). "AKT1 and MAPK1 genes had significantly higher expression levels in PDAC cancer samples than in normal samples (*p < 0.01), whereas mTOR expression was not significantly different." (PMID 38553450, 2024). "A structure-based computational study against the HeLa cancer cell related protein targets (BCL-2 (4MAN), AKT-1 (4GV1), MCL-1 (5FDO), and BRAF (5VAM)) was used to determine the most potent biomarker." (PMID 40190673, 2024). "The PIK3CA and AKT1 genes are involved in the PI3K/AKT signaling pathway, which influences multiple pathways related to carcinogenesis and cancer progression." (PMID 39329961, 2024). "Among 13 luminal B samples, two tumors presented just one cancer driver, i.e., PIK3CA (oncogene) in one of the tumors, and AKT1 (oncogene) in the other." (PMID 39208653, 2024). "More importantly, EGFR, AKT1, and STAT3 are well-known biomarkers of cancer, but the effects of genistein on these targets remain elusive." (PMID 38731403, 2024). "Capivasertib (AZD5363) is a selective ATP-competitive AKT inhibitor that targets AKT1, AKT2, and AKT3, demonstrating potential for use in various cancers, including HER2+ BC." (PMID 39769140, 2024). "DAB2IP is inactivated in cancers through promoter methylation involving the EZH2-PRC2 complex, phosphorylation by AKT1, posttranscriptional silencing by microRNAs, and degradation by E3-ubiquitin ligases." (PMID 39418101, 2024). "The serine/threonine kinase AKT, also known as protein kinase B (PKB), is a proto-oncogene that has three isoforms, AKT1 (PKBα), AKT2 (PKBβ), and AKT3 (Pub), which have markedly different or even opposing functions in cancer and physiology." (PMID 38375094, 2024).
cancer (continued). "In addition, this miRNA downstream target NCAPH can compete with Akt1 to form a complex with β-catenin, which prevents β-catenin phosphorylation and ubiquitin interceded protein destruction, resulting in triggered Wnt signaling and a more favorable niche for cancer stem cells in NSCLC." (PMID 37986065, 2023). "Since BAG5 amplification correlated with Akt1 protein expression, we identified and compared the top ten correlated DUBs and E3 ligases with BAG5 in general and in amplified BAG5 cancer patients." (PMID 38139359, 2023). "The advantage of developing dual inhibitors of AKT1 and PI3K is that both proteins are involved in the same signaling pathway and play critical roles in the proliferation and survival of cancer cells." (PMID 37513905, 2023). "In the sample of patient B19, four cancer related genes CCR7, AKT1, SLIT2 and CDK6 were found with HPV integrations before treatment, and none was found after treatment." (PMID 37914994, 2023). "The role of AKT1, a downstream element of the phosphoinositide-3-kinase (PI3K) cascade, in the upregulation of ABCB1 is strongly established in cancer models in link with chemotherapeutic resistance mechanism." (PMID 37408070, 2023). "From the network pharmacology analysis, it was found that the main targets for inhibiting BPH are AKT1, TNF, EGFR, STAT3 and PTGS2, which are enriched in pathways in cancer." (PMID 37446563, 2023). "Immunohistochemical analysis showed that 6 gene (NLRX1, AKT1, CSRP1, LEP, MUC4 and SEMA4B) of 10 genes were abnormal expressions between cancer and paracancer tissue." (PMID 36817485, 2023). "The best analog produced by this work was compound 19, endowed with an IC50 of 0.038 μM on isolated AKT1 and low micromolar anti-proliferative activity on OVCAR-8, HL60, and HCT-116 cancer cell lines (8.1, 5.3, and 8.9 μM, respectively)." (PMID 37513905, 2023). "Different signaling paths with translational impacts in cancer-stem-like cells have been recognized in SDF1/CXCR4 interactions, including AKT-1." (PMID 36986504, 2023). "AKT1 and mTOR genes had significantly higher expression levels in PDAC cancer samples than in normal samples (*P< 0.01), whereas mTOR expression was not significantly different." (PMID 37503215, 2023). "Heat-killed S. cerevisiae induced apoptosis in cancer cells, the SW480 cell line, by up-regulating Bax, cleaved caspase 3 and cleaved caspase 9, and down-regulating p-Akt1, Bcl-XL, Rel A, procaspase 3 and procaspase 9 expressions." (PMID 37664108, 2023). "PIK3CA and AKT1/2 are two of the main members of the PI3K/AKT/mTOR signalling pathway, which is often activated in a range of cancers and contributes to their development." (PMID 37352361, 2023). "Similarly, the expression levels of both miR-143-3p and AKT1 in tumor tissue is significantly correlated with survival outcomes in several other TCGA patient cohorts, indicating that they could also be a useful prognostic biomarker for different cancers." (PMID 37759434, 2023). "PIK3R1 and AKT1 both belong to the PI3K pathway, which is the most frequently altered pathway in cancer." (PMID 37895906, 2023). "A small-molecule Comp34 preferentially targeted TNBC and cancer stem cells and inhibited AKT1/mTOR expression by inhibition of lncRNA NUDT3-AS4, which sponged miR-99s to release the mRNA of AKT1/mTOR from miRNA-dependent decay." (PMID 37686205, 2023). "Nine of ten anti-COVID-19 core targets (HIF1A, EGFR, CASP3, AKT1, MAPK1, MAPK3, HSP90AA1, mTOR, and IL-6) followed the pathways in cancer." (PMID 36817449, 2023). "Analysis of the site of expression revealed the existence of AKT1, MTDH, and NCOR2 genes in the colorectum and presence of TGFBR1 and MTDH in various cancer cell lines such as A-549 and HeLa." (PMID 36499586, 2022). "The top-ranked pathways associated with cancer and cell proliferation are highly enriched with the DEGs, such as PIK3AP1, LABM3, AKT1, MYB in “PI3K-AKT pathway” (32%) and “pathways in cancer” (20%)." (PMID 36075900, 2022).
cancer (continued). "Compelling findings provided evidence that TRIB3 linked stress signals are capable of promoting tumor initiation and progression by supporting cancer stemness, which is coordinated with elevated FOXO1 and AKT1 axis." (PMID 35473511, 2022). "AKT1, EGFR, SRC, ESR1, and PTGS2 are the top five targets in the PPI network, and they were reported as critical regulatory factors in cancer metastasis and EMT." (PMID 35942366, 2022). "Target gene analysis for these tsRNAs showed them to be cancer-related involving TGF-β and Wnt-signalling-pathways as well as regulating genes AKT1, MRAS, and WNT4." (PMID 35409051, 2022). "While all isoforms seem to downregulate autophagy, AKT1 and AKT3 seem to be involved in cell proliferation and AKT1 and AKT2 in the regulation of the cancer cell metabolism." (PMID 35053468, 2022). "A careful examination of more cell functions influenced by more AKT1-, AKT2-, and AKT3-targeting circRNAs on cancer cells is warranted." (PMID 36230902, 2022). "Potential targets of statins for cancer treatment identified by LIGHTHOUSE included STAT3, CCND1, AKT1, and CCL2." (PMID 36246574, 2022). "Among the common kinases, the mTOR, AKT1, SRC, FYN, and GNB2L1 are the kinases that are common in ALS and cancers and also identified as hub genes from the PPI network." (PMID 36590916, 2022). "Although many circRNAs were shown to target AKT1, AKT2, and AKT3, only some were capable of modulating cell functions (apoptosis and migration) in cancer cells based on the literature search." (PMID 36230902, 2022). "In the PPI network, the core targets, including AKT1, CREB1, CDC42, SIRT1, PIK3CA, and MMP9, are key cancer‐related genes, which further indicate the important role of miR‐204‐5p in human cancers." (PMID 35908280, 2022). "Centrality analysis showed that there are three common hub nodes, i.e. AKT1, PTEN, and GAPDH, for the three investigated cancers." (PMID 35611247, 2022). "Some members of this pathway, including the two most important factors of PI3K/AKT pathway AKT1 and PI3K, are reported to be direct targets of miR‐204‐5p in multiple cancer types." (PMID 35908280, 2022). "To date, three isoforms have been isolated, named AKT1, AKT2 and AKT3, and the different isoforms are believed to mediate critical functions in cancer pathophysiology." (PMID 35996134, 2022). "As the AKT pathway has been shown to be stimulated in cancer cells by growth factors, we chose to use EGF as a mitogen to stimulate the AKT1 pathway in MCF-7 cells." (PMID 35892586, 2022). "AKT1, PTEN, and GAPDH were identified as common proteins for the three cancers (common central nodes) and were included in the ten top individuals based on degree value." (PMID 35611247, 2022). "At the same time, previous studies have confirmed that the downstream genes of LNC00324 can induce cancer cells to develop resistance to chemotherapy, including IGF-1R, AKT1, and STAT3." (PMID 36620587, 2022). "The PPI network also indicated that AKT1 and MYC are two hub proteins for cancer progression and metastasis, and the Western blot analysis of AKT activation and MYC expression was employed to reconfirm these prediction data." (PMID 34944720, 2021). "In cancer tissues, the inhibitory effect of 17-DMAG on AKT1/ERK signaling pathways was then investigated." (PMID 35095481, 2021). "It has three different subtypes, AKT1, AKT2, and AKT3, which are closely related to the development of human cancer." (PMID 34956562, 2021). "With respect to HT-29 cancer cells, treatment with KA39 at a TGI concentration of 15.9 μΜ for 3 and 24 h induced significant inhibition of Akt1 phosphorylation, decreasing the Akt1 phospho-form by 72.9% and 88.5%, respectively (p < 0.01)." (PMID 33916378, 2021).